VKORC1 (vitamin K epoxide reductase complex subunit 1)
Description:
Involved in vitamin K metabolism. Catalytic subunit of the vitamin K epoxide reductase (VKOR) complex which reduces inactive vitamin K 2,3-epoxide to active vitamin K. Vitamin K is required for the gamma-carboxylation of various proteins, including clotting factors, and is required for normal blood coagulation, but also for normal bone development.
Synonyms: VKOR; EDTP308; MST134; MST576; VKCFD2
Tractability: Small molecule: an approved drug acts on it; a structure with a bound ligand is known; a high-quality ligand is known; it belongs to a druggable protein family. Antibody: UniProt predicts a signal peptide or a membrane-spanning region. PROTAC: its protein half-life has been measured; a small molecule that binds it is known.
Target class: Enzyme; Oxidoreductase
Safety:
Unwanted effects reported when the protein is acted on. In parentheses: how it was acted on, where the effect was seen, and who reports it.
hemorrhage (source: ClinPGx)
adverse events (source: ClinPGx)
bleeding (source: ClinPGx)
over-anticoagulation (source: ClinPGx)
Gene: Protein-coding gene on chromosome 16 (31,090,842 to 31,095,980, reverse strand). Ensembl gene ENSG00000167397.
Subcellular location: Endoplasmic reticulum membrane
Subcellular location (Human Protein Atlas): Endoplasmic reticulum
Pathways (Reactome):
Metabolism: Metabolism of vitamin K
Gene Ontology:
Molecular function: protein binding; vitamin-K-epoxide reductase (warfarin-insensitive) activity; vitamin-K-epoxide reductase (warfarin-sensitive) activity; oxidoreductase activity, acting on CH or CH2 groups, disulfide as acceptor
Biological process: blood coagulation; peptidyl-glutamic acid carboxylation; vitamin K metabolic process; xenobiotic metabolic process; bone development
Cellular component: endoplasmic reticulum; endoplasmic reticulum membrane; endoplasmic reticulum lumen
Genetic constraint (gnomAD): Loss-of-function variants: 12 observed, 16.58 expected, observed/expected ratio (o/e) 0.72, 90% interval 0.46 to 1.17. The upper end of that interval is the gene's LOEUF score, 1.17, which puts it in group 5 of 6, group 1 being the genes least tolerant of losing a copy. Missense variants: 223 observed, 218.93 expected, observed/expected ratio (o/e) 1.02, 90% interval 0.91 to 1.14. Synonymous variants: 94 observed, 90.96 expected, observed/expected ratio (o/e) 1.03, 90% interval 0.87 to 1.23.
Gene-disease validity (ClinGen):
ClinGen rates the evidence that VKORC1 causes each of these diseases.
vitamin K-dependent clotting factors, combined deficiency of, type 2 (autosomal recessive): Moderate.
Homologues: Orthologues: chimpanzee VKORC1 (100% identical), dog VKORC1 (91% identical), rabbit VKORC1 (88% identical), guinea pig VKORC1 (88% identical), pig VKORC1 (86% identical), mouse Vkorc1 (85% identical), tropical clawed frog vkorc1 (53% identical), zebrafish vkorc1 (53% identical), Drosophila melanogaster Vkor (36% identical). Paralogues in human: VKORC1L1 (45% identical).
Diseases named in the same sentence as VKORC1 in open-access papers:
VKORC1 is named in the same sentence as 83 diseases in open-access papers, as found by Europe PMC text mining. Sharing a sentence is not in itself a finding about the gene and the disease. The quoted sentences say what the papers report.
atrial fibrillation (10 papers, 2017 to 2025). A disorder characterized by an electrocardiographic finding of a supraventricular arrhythmia characterized by the replacement of consistent P waves by rapid oscillations or fibrillatory waves that vary in size, shape and timing and are accompanied by an irregular ventricular response. "Greater bleeding risk among variant carriers in CYP2C9 and VKORC1 was clearly demonstrated in the Effective Anticoagulation with Factor Xa Next Generation in Atrial Fibrillation-Thrombolysis in Myocardial Infarction 48 (ENGAGE AF-TIMI 48) clinical trial that compared edoxaban vs. warfarin." (PMID 29236081, 2017). "The entire CYP2C9 gene region was sequenced in 1,993 individuals, and clinical data and VKORC1 genotypes were collected from 986 patients with atrial fibrillation treated with warfarin." (PMID 36505370, 2022). "In 2015, Park and colleagues collected data from 380 Korean patients with atrial fibrillation and evaluated genetic (CYP2C9 and VKORC1) and non-genetic (SAMe-TT2R2 score) factors associated with TTR." (PMID 32274641, 2020). "We aimed to assess impact of three important genes participating in vitamin K cycle (i.e. VKORC1 rs9923231, CYP4F2 rs2108622 and NQO1 rs1800566) on the daily stable warfarin dose requirement in Sichuan Han Chinese patients with catheter ablation of atrial fibrillation." (PMID 29776386, 2018).
diabetes (9 papers, 2014 to 2025). "And the adjusted R2 values observed were modest (~0.28–0.30), indicating that VKORC1 polymorphisms explain only a small proportion of the variability in arterial stiffness, similar to other multifactorial traits like hypertension and diabetes." (PMID 41465069, 2025). "Our model that includes non-genetic factors such as age, diabetes and hypertension as well as genetic variants in VKORC1 (rs9923231), CYP2C9 (rs2860905 and 1856908), CES2 (rs4783745), and ABCB1 (rs10276036), explained 60% of the variability in warfarin dose requirements among Puerto Ricans." (PMID 28638342, 2017). "Warfarin and the influence of CYP2C9/VKORC1 genes: Although not primarily intended as a diabetes treatment, warfarin is frequently prescribed to individuals with diabetes to mitigate the risk of thrombosis." (PMID 37724233, 2023).
Hypertension (9 papers, 2014 to 2025). The presence of chronic increased pressure in the systemic arterial system. "The PTV rs2884737 in VKORC1 associated with hypertension is in moderate LD (R2 ≈ 0.56) with several nearby common variants and the PTV rs776746 in CYP3A5 associated with hayfever/allergic rhinitis is in near perfect LD with one other nearby variant." (PMID 29691392, 2018). "The presence of SNPs in VKORC1 or CYP4F2 genes significantly increased the risk of ischemic stroke in the context of smoking, arterial hypertension, and carotid plaque burden." (PMID 37653796, 2023). "We identified additional protective associations between PTVs in IFIH1 and hypothyroidism (labeled as hypothyroidism/myxedema) (MAF = 1.5%, p = 1.7 × 10−6, OR = 0.80, 95% CI: 0.73–0.88) and VKORC1 and hypertension (MAF = 25.3%, p = 1.4 × 10−6, OR = 0.97, 95% CI: 0.96–0.98)." (PMID 29691392, 2018).
Stroke (9 papers, 2010 to 2023). Sudden impairment of blood flow to a part of the brain due to occlusion or rupture of an artery to the brain. "Authors discovered that VKORC1 2255C allele, which can reflect G-C-G-C-A haplotype, increased almost twice the risk of stroke, coronary heart disease, and aortic dissection in Chinese population." (PMID 27703968, 2016). "Polymorphisms in the VKORC1 (−1639G > A) m/m genotype, the CYP4F2 (1347C > T) w/m and m/m genotypes, and history of MI were also linked to stroke, but following Bonferroni correction, the P value threshold was slightly exceeded." (PMID 37653796, 2023). "The VKORC1 and CYP4F2 homozygous genotypes were also more frequent in stroke patients and increased the risk of stroke when they were found in patients with specific comorbidities or conditions." (PMID 37653796, 2023). "The VKORC1 and CYP4F2 homozygous genotypes were associated with an increased risk of stroke, even though the threshold for statistical significance was slightly exceeded in the multivariate model." (PMID 37653796, 2023). "In conclusion, variants in VKORC1 and CYP2C9 are associated with acenocoumarol maintenance dose, stroke recurrence and ICH in a Spanish cohort." (PMID 32071341, 2020). "With this sample size we have been able to detect variants in or near VKORC1 and CYP2C9 associated with acenocoumarol dose, stroke recurrence, and ICH in a Spanish cohort." (PMID 32071341, 2020). "Genetic variability could be a cause of susceptibility to recurrent stroke in patients with AF: 2 genes (CYP2C9 and VKORC1) may play a role in individual patient response to and efficacy of VKA,30, 31, 32, 33 but no such variability of response is known for DOACs." (PMID 32052481, 2020). "The VKORC1 −1639G > A mutant and CYP4F2 1347C > T m/m genotypes were more frequently encountered in the stroke group, although in the case of CYP4F2 m/m, the threshold for statistical significance was slightly exceeded." (PMID 37653796, 2023). "The second paper evaluated the roles of VKORC1, gamma-glutamyl carboxylase (GGCX), calumenin (CALU), and cytochrome P450 2C9 (CYP2C9) in warfarin maintenance dose on Japanese stroke sufferers." (PMID 22135769, 2011).
osteoporosis (6 papers, 2010 to 2026). A condition of reduced bone mass, with decreased cortical thickness and a decrease in the number and size of the trabeculae of cancellous bone (but normal chemical composition), resulting in increased fracture incidence. "The overall effect of VKORC1 risk alleles on osteopenia/osteoporosis was significant with a p = 0.041 (fixed effects OR = 1.16, 95% CI = 1.01-1.35)." (PMID 41597466, 2026). "Materials and Methods: A systematic review and meta-analysis were conducted to evaluate the association between VKORC1 polymorphisms and osteopenia and osteoporosis." (PMID 41597466, 2026). "Reduced functionality of VKORC1 is associated with osteoporosis and calcified plaques in the carotid artery." (PMID 38674033, 2024). "Several studies also delineate that mutations of VKORC1 are associated with bone mineral density and osteoporosis." (PMID 32394619, 2020). "In our study, the association of the VKORC1 gene polymorphisms with both osteoporosis and osteoporotic fractures was examined." (PMID 30892416, 2019). "The present study was planned to demonstrate a possible relationship between vertebral fracture and polymorphisms of the VKORC1 gene in osteoporosis." (PMID 30892416, 2019). "In studies that have investigated the association between BMD, atherosclerosis and VKORC1 1173 C>T polymorphisms in patients with osteoporosis or osteopenia, a high frequency of the TT genotype has been found in VKORC1 1173 C>T polymorphisms." (PMID 30892416, 2019). "This is the first report of an association between BMD and osteoporosis and these VKORC1 SNPs in the literature." (PMID 21179439, 2010). "However, there have been few studies on the association between osteoporosis and polymorphisms of the VKORC1 enzyme 11,17." (PMID 30892416, 2019). "Therefore, we aimed to investigate VKORC1 9041 G/A and 3673 G/A polymorphisms that varied among populations in osteoporosis and postosteoporotic vertebral fractures in Turkish women with postmenopausal osteoporosis." (PMID 30892416, 2019). "In this study, the relationship between osteoporotic vertebral fractures and 9041 Guanine/Adenine and 3673 Guanine/Adenine polymorphisms related to the vitamin K epoxide reductase complex subunit-1 (VKORC1) gene in postmenopausal women with osteoporosis was investigated." (PMID 30892416, 2019). "We also tested for associations between VKORC1 SNPs and osteoporosis, an extreme phenotype of BMD." (PMID 21179439, 2010). "No statistical significance was found between genotypes of SOST rs1234612 and VKORC1 rs9934438 with BMD in postmenopausal Romanian women with osteoporosis." (PMID 31774873, 2019). "This is the first report of VKORC1 common genetic variation associated with BMD, and one of the few reports available that investigate the genetics of BMD and osteoporosis in diverse populations." (PMID 21179439, 2010). "Our results suggest that common variants in VKORC1 are indeed associated with BMD and perhaps osteoporosis, but many of these results are limited to African Americans." (PMID 21179439, 2010). "The TT genotype is more common in the osteoporotic group than in the osteopenic group, and the TT genotype of VKORC1 1173 C>T could be a potential genetic marker for osteoporosis." (PMID 30892416, 2019). "This study aimed to assess the relationship between bone mineral density and genotypes of four polymorphisms in previously detected osteoporosis-candidate genes (FDPS rs2297480, LRP5 rs3736228, SOST rs1234612, VKORC1 rs9934438) in postmenopausal Romanian women with primary osteoporosis." (PMID 31774873, 2019). "We then tested for associations between VKORC1 SNPs and osteoporosis, but the results did not mirror the associations observed between VKORC1 and BMD, possibly due to small numbers of cases." (PMID 21179439, 2010). "Given that VKORC1 SNPs were associated with BMD total region, we tested whether VKORC1 SNPs were associated with osteoporosis." (PMID 21179439, 2010).
osteoporosis (continued). "Genetic variants in VKORC1 may influence bone mineral density (BMD) and osteoporosis risk." (PMID 41597466, 2026). "Moreover, considering that BMD distribution varies per population, genetic variants of the VKORC1 gene may be associated with BMD and osteoporosis." (PMID 30892416, 2019). "This is the first report of VKORC1 SNPs associated with BMD; therefore, further studies are required to replicate and characterize the association to establish this candidate gene as a locus relevant to BMD and perhaps associated phenotypes such as osteoporosis." (PMID 21179439, 2010). "The purpose of the present study is to evaluate the relation between BMD and genotypes of four SNPs in previously reported osteoporosis candidate-genes (FDPS rs2297480, LRP5 rs3736228, SOST rs1234612, VKORC1 rs9934438) in a cohort of postmenopausal Romanian women." (PMID 31774873, 2019). "The weak contribution of VKORC1 SNPs on BMD and osteoporosis is not surprising given that BMD and osteoporosis are complex traits likely influenced by both genetics and the environment." (PMID 21179439, 2010).
coagulopathy (5 papers, 2012 to 2025). "Clearly therefore other mechanisms linking the VKORC1- ORF7a interaction to COVID-19 pathogenesis and coagulopathy warrant consideration." (PMID 33730015, 2021). "Patient stratification is also employed for treatment of coagulation disorders with warfarin based on CYP2C9, vitamin K epoxide reductase complex, subunit 1 (VKORC1) and Protein C status, and international normalized ratio values determined throughout the period of the treatment." (PMID 22911518, 2012).
thromboembolic disease (5 papers, 2012 to 2025). "Human VKORc1 catalyzes the regeneration of active vitamin K to support blood coagulation and is the target of oral vitamin K antagonists such as warfarin, which is widely used to treat and prevent thromboembolic diseases." (PMID 40741763, 2025).
venous thromboembolism (5 papers, 2012 to 2025). Occlusion of the lumen of a vein by a thrombus that has migrated from a distal site via the blood stream. "The genotype-guided dosing algorithm included clinical variables and genotyping for CYP2C9 and VKORC1 and the control-dosing algorithm included only clinical variables for the initiation of acenocoumarol or phenprocoumon treatment in patients with AF or venous thromboembolism." (PMID 30939847, 2019). "The aim of this study is to evaluate the effectiveness and efficiency of an acenocoumarol dosing algorithm developed by our group which includes demographic, clinical and pharmacogenetic variables (VKORC1, CYP2C9, CYP4F2 and ApoE) in patients with venous thromboembolism (VTE)." (PMID 23237631, 2012).
chronic kidney disease (4 papers, 2023 to 2025). Impairment of the renal function secondary to chronic kidney damage persisting for three or more months. "For example, during the development of rat chronic kidney disease (CKD), renal MK-4 levels rose, but UBIAD1 and VKORC1 expression decreased." (PMID 39057059, 2024).
COVID-19 (4 papers, 2021 to 2024). A disease caused by infection with severe acute respiratory syndrome coronavirus 2. "To study the role of coagulation in COVID-19 pathogenesis, we explored the interactions of VKORC1, SERPING1 and PABPC4 with viral proteins through computational docking." (PMID 33730015, 2021). "We focused on the impact of VKORC1, SERPING1, and PABPC4 gene variants on COVID-19 severity." (PMID 33730015, 2021). "In addition, we found that VKORC1 expression in nasal secretory AECs was higher in symptomatic patients than in asymptomatic patients (all P < 0.05), but was comparable among patients with mild, moderate and severe COVID-19 symptom (all P > 0.05)." (PMID 37301869, 2023). "Having revealed the expression profile of DCM’s targets (NQO1 and VKORC1) in AECs, we then explored whether the NQO1 and VKORC1 expressions in AECs correlated with the COVID-19 severity in clinical patients." (PMID 37301869, 2023).
myocardial infarction (4 papers, 2008 to 2025). Gross necrosis of the myocardium, as a result of interruption of the blood supply to the area, as in coronary thrombosis. "CYP2C9 and VKORC1 genotype frequencies in myocardial infarction patients appear similar to other patient groups and have similar impact on warfarin maintenance dose." (PMID 18559094, 2008). "The primary aim of the present study was to investigate the relation between genotypes of CYP2C9 and VKORC1 and warfarin maintenance dose in myocardial infarction." (PMID 18559094, 2008). "The primary aim of the present study was to investigate the relation between genotypes of CYP2C9 and VKORC1 and warfarin maintenance dose in myocardial infarction patients (from the WARIS-II study)." (PMID 18559094, 2008). "This study was designed to investigate the frequency of CYP2C9 and VKORC1 gene polymorphisms and their relation to warfarin dose and INR in patients with myocardial infarction from the Norwegian WARIS-II study." (PMID 18559094, 2008). "In conclusion, the observed genotype frequencies of CYP2C9 and VKORC1 in patients with myocardial infarction are similar to those previously reported in other patient groups and healthy subjects in Caucasians, as is the relation between warfarin dosage and genotypes." (PMID 18559094, 2008).
Obesity (4 papers, 2018 to 2025). Accumulation of substantial excess body fat. "For example, we find that the AA genotype of VKORC1 plays a more important role in determine VTE occurrence for obesity or morbidly obesity individuals than for people from the other BMI categories." (PMID 32645000, 2020). "Instead, our screen suggests that different nearby cis gene may be more fruitful for further functional follow up for obesity, namely ZCCHC8, VPS33A, RSRC2; SPDEF, NUDT3; SETD1, VKORC1; SGSM2, SRR; VASP, SIX5; OTX1; BANK1; ARIH1; ELL; CHST8, respectively." (PMID 29608557, 2018).
breast carcinoma (3 papers, 2014 to 2023). "All three genes involved in the vitamin K cycle (GGCX, VKORC1, and VKORC1L1) are expressed in normal mouse mammary gland yet there is no published data regarding their expression in human breast or breast cancer." (PMID 31040920, 2019). "To mechanistically address the role of vitamin K and γ-carboxylation in breast cancer, we screened a panel of breast cancer cell models for GGCX, VKORC1, and VKORC1L1 expression." (PMID 31040920, 2019). "To gain insight into the potential impact of the vitamin K pathway in breast cancer, we annotated expression of GGCX, VKORC1, and VKORC1L1, profiled GLA protein modifications, and directly compared the effects of K1 and K2 in multiple breast cancer model systems." (PMID 31040920, 2019). "To explore the relevance of γ-carboxylation in breast cancer, we first analyzed datasets from The Cancer Genome Atlas (TCGA) and found that approximately 25% of 1098 invasive breast cancers exhibit amplification or up-regulation of GGCX, VKORC1, and/or VKORC1L1." (PMID 31040920, 2019).